CYP27A1 (cytochrome P450 family 27 subfamily A member 1)
Diseases named in the same sentence as CYP27A1 in open-access papers (continued):
Sharing a sentence is not in itself a finding about the gene and the disease.
leukopenia (5 papers, 2021 to 2025). "The CYP27A1 rs17470271 variant was reported in only a few studies, including a study from China, which linked it with leukopenia in patients with pulmonary tuberculosis." (PMID 40708646, 2025). "Our previous study revealed that the CYP27A1 rs17470271 and rs933994 T alleles were significantly associated with leukopenia and drug resistance in PTB patients, respectively." (PMID 36483566, 2022). "In CYP27A1, the rs17470271 T and rs933994 T alleles were significantly associated with leukopenia, drug resistance in the PTB patients, respectively." (PMID 33882819, 2021). "For CYP27A1 gene, the rs17470271 T allele frequency was significantly lower with leukopenia (P = 0.039), and the rs933994 T allele frequency was significantly decreased with drug resistance (P = 0.047)." (PMID 33882819, 2021). "Our previous studies showed that CYP27A1 gene rs17470271 T; rs933994 T allele frequencies were respectively significantly related to leukopenia, drug resistance, and lncRNA NEAT1 gene rs3825071 TT genotype; T allele frequencies were significantly increased in sputum smear-positive PTB patients." (PMID 36275653, 2022). "We also investigated the possible association between these SNPs and clinical features of the PTB patients, and found that CYP27A1 rs17470271 T allele and rs933994 T allele frequencies were significantly associated with leukopenia, drug resistance in PTB patients, respectively." (PMID 33882819, 2021). "In addition, the results of another study suggested that CYP27A1 rs17470271, rs933994 variants might affect the development of leukopenia, drug resistance in PTB patients, respectively." (PMID 36619747, 2022). "Moreover, several SNPs in CYP27A1, GC, and DHCR7 genes were related to multiple clinical features, including leukopenia, drug resistance, pulmonary infection, fever, and DILI, in PTB patients." (PMID 33882819, 2021).
steatosis (5 papers, 2018 to 2024). Increased lipid within the cytoplasm of cells. "THCC was found to inhibit Cyp27a1 mRNA expression in goose liver cells, and CYP27A1 can inhibit steatosis." (PMID 38506086, 2024). "In a diet-induced steatosis model, CH25H has been reported to positively regulate CYP7A1 and CYP27A1 and reduce small heterodimer partner (SHP), thus increasing the synthesis and excretion of BAs, drastically reducing the high-fat diet-induced hepatic steatosis." (PMID 39287458, 2024).
xanthomatosis (5 papers, 2016 to 2025). A condition marked by the development of widespread xanthomas, yellow tumor-like structures filled with lipid deposits. "When we performed mutational analysis of all 9 exons of CYP27A1 in our Japanese patient with late-onset xanthomatosis with longitudinally extensive spinal cord lesion, we found one novel (Q85R) and one previously reported CTX-associated missense mutation (R405Q)." (PMID 26861945, 2016).
Alzheimer disease (4 papers, 2021 to 2024). A progressive, neurodegenerative disease characterized by loss of function and death of nerve cells in several areas of the brain leading to loss of cognitive function such as memory and language. "The product of the CYP27A1 reaction, 27-hydroxycholesterol, is considered to increase oxidative stress and to induce Alzheimer’s disease as well as PD." (PMID 39403150, 2024). "Metabolomic studies in post-mortem Alzheimer’s disease (AD) brain samples presented an enhanced brain-specific CYP27A1 activity with a relatively higher ratio of TCA, DCA, LCA, TDCA, and GDCA." (PMID 36816113, 2023). "Consistently, Ad-MAFG infection decreased the luciferase activities of the reporters containing Cyp7b1, Cyp8b1, and Cyp27a1 promoters in hepatocytes, respectively." (PMID 33754066, 2021).
dyslipidemia (4 papers, 2015 to 2023). "We have shown in vivo that CYP27A1 inhibitors decrease the growth of ER-positive breast tumors, but the findings in this study suggest that they may have broader utility as cancer treatments, especially in the background of dyslipidemia." (PMID 34429409, 2021). "In addition, variants in genes causing other dyslipidemias showing phenotypes overlapping with FH may mimic FH in patients without causative variants (FH-phenocopies; ABCG5, ABCG8, CYP27A1 and LIPA genes) or act as phenotype modifiers in patients with a pathogenic variant in a causative gene." (PMID 36834635, 2023).
glioma (4 papers, 2013 to 2020). A benign or malignant brain and spinal cord tumor that arises from glial cells (astrocytes, oligodendrocytes, ependymal cells). "To further explore the role of the vitamin D metabolic pathway in glioma, we examined the expression of vitamin D receptors and CYP27A1 and CYP27B1, key enzymes involved in synthesis of 25(OH)D3 and 1α,25(OH)2D3 in glioma tissues." (PMID 30631035, 2019). "The expression of CYP27A1 is relatively low in high level glioma tissue, the expression of CYP27B1 is elevated in glioma tissues and increased significantly in grade IV glioma tissue." (PMID 30631035, 2019). "Additionally, analysis based on 1,018 Chinese glioma patients suggested that CELF5 (P < 0.001), GSG1L (P = 0.002), AMACR (P < 0.001), CYP27A1 (P < 0.001), CYP46A1 (P < 0.001), and CH25H (P = 0.046) were all prognostic indicators in Kaplan-Meier survival analysis." (PMID 32117422, 2019).
liver fibrosis (4 papers, 2018 to 2025). "Moreover, the down-regulated CYP-27A1 mRNA expression level was found to be involved with liver fibrosis." (PMID 35656170, 2022). "CerS5 knockout not only reduces the expression of the key enzyme Cyp27a1 but also elevates the levels of 12a-OH BAs, specifically CAs and DCAs, which play a role in HSC activation and the advancement of liver fibrosis." (PMID 40557038, 2025).
ovarian carcinoma (4 papers, 2015 to 2025). A malignant neoplasm originating from the surface ovarian epithelium. "High CYP27A1 expression is associated with poor prognosis at the early stages of disease and poorer progression-free survival but serves as a positive predictor in late-stage ovarian cancer." (PMID 34820325, 2021). "Intriguingly, however, CYP27A1 or exogenous 27HC treatment in the ovarian cancer mouse model has also been shown to augment peritoneal tumor spread and carboplatin resistance, consistent with Kaplan–Meier analyses of CYP27A1 in ovarian cancer patients." (PMID 34820325, 2021).
renal clear cell carcinoma (4 papers, 2023 to 2025). "The loss of function of the enzyme CYP27A1 has been reported in certain types of cancer, such as bladder urothelial carcinoma, breast invasive ductal carcinoma, renal clear cell carcinoma, prostate adenocarcinoma and cutaneous melanoma." (PMID 37508912, 2023). "In agreement, CYP27A1 was found to inhibit proliferation and migration of clear cell renal cell carcinoma by activating the LXRs/ABCA1 pathway." (PMID 37210507, 2023).
asthma (3 papers, 2017 to 2020). "They include RBM42, STX5, and TRIM41 in asthma, CYP27A1, GM2A, LGALS9, SPI1, and NLRC4 in COPD, as well as ATF3, PPP1R15A, ZFP36, SOCS3, NAMPT, and GADD45B in IPF." (PMID 31952466, 2020). "Another study reported an association between a CYP2R1 variant and FEV1 in children, and between specific haplotypes on CYP2R1 and CYP27A1 and asthma phenotypes." (PMID 28486474, 2017). "SNPs in the vitamin D pathway (CYP27A1, CYP27B1, CYP2R1, CYP24A1, and GC) affecting 25OHD levels demonstrated moderate effects on risk of asthma in a prior adult study, but the role of these variants on asthma risk later in life is unknown." (PMID 28486474, 2017). "These genes included RBM42, STX5, and TRIM41 in asthma, CYP27A1, GM2A, LGALS9, SPI1, and NLRC4 in COPD, ATF3, PPP1R15A, ZFP36, SOCS3, NAMPT, and GADD45B in IPF, LRRC48 and CETN2 in asthma-COPD, COL15A1, GIMAP6, and JAM2 in asthma-IPF and LMO7, TSPAN13, LAMA3, and ANXA3 in COPD-IPF." (PMID 31952466, 2020).
atopic eczema (3 papers, 2015 to 2026). A common chronic pruritic inflammatory skin disease with a strong genetic component. "In a large cohort study of 1442 Chinese children with eczema and 1231 non-allergic controls, atopic eczema was associated with a vitamin D-related SNP rs4674343 on CYP27A1 (odds ratio 0.66, 95% confidence interval 0.53–0.83, p = 0.0004)." (PMID 26239464, 2015).
colon carcinoma (3 papers, 2017 to 2021). "CYP27A1, a cytochrome P450 oxidase family member, is closely related to the proliferation of multiple tumor cells, such as prostate, breast and colon cancer." (PMID 34178023, 2021). "The presented experiments using SW-620 colon carcinoma cells revealed a time-dependent formation of 7k27OHC by CYP27A1 and 11β-HSD2 from 7βOHC, with an accumulation of 7β27OHC upon inhibition of 11β-HSD2." (PMID 31273032, 2019). "Because reductive reactions by reactive oxygen species are highly unlikely, we tested the hypothesis of 27-hydroxylation of 7βOHC and subsequent oxidation to 7k27OHC in SW-620 colon cancer cells endogenously expressing CYP27A1 and 11β-HSD2." (PMID 31273032, 2019).
Hepatic steatosis (3 papers, 2022 to 2024). Steatosis is a term used to denote lipid accumulation within hepatocytes. "In regard to hepatic steatosis, Hyp attenuated the lipid accumulation in liver by preserving hepatic lipid and bile acid homeostasis via the regulation of PPARγ, FXR, LXRα, ACC, SREBP, cholesterol 7α-hydroxylase (CYP7A1), and CYP27A1." (PMID 35892639, 2022).
hepatocellular carcinoma (3 papers, 2021 to 2025). A malignant tumor that arises from hepatocytes. "GSEA employing the c2.all.v2022.1.Hs.symbols.gmt curated gene set further revealed that disulfidoptosis in hepatocellular carcinoma is fundamentally orchestrated by hepatic metabolic reprogramming, notably suppression of bile acid biosynthesis (e.g., CYP7A1/CYP27A1)." (PMID 40790550, 2025).
liver inflammation (3 papers, 2019 to 2025). "Furthermore, hematopoietic overexpression of CYP27A1 in the same mouse model was able to rescue the diet-induced liver inflammation." (PMID 31113816, 2019).
lung adenocarcinoma (3 papers, 2023 to 2024). A carcinoma that arises from the lung and is characterized by the presence of malignant glandular epithelial cells. "Several studies revealed a substantial reduction in CYP27A1 expression, which is associated with CE metabolism, in lung adenocarcinoma cells compared to healthy cells." (PMID 39083563, 2024). "Since our previous findings have confirmed that 27HC-stimulated conditional medium of lung adenocarcinoma cells promotes osteoclast differentiation, and CYP27A1 is a synthetase of 27HC, we speculated that CYP27A1 KO might affect osteoclast differentiation." (PMID 36890868, 2023). "Moreover, a negative correlation exists between CYP27A1 expression and the extent of metastasis of lung adenocarcinoma cells." (PMID 39083563, 2024).
memory impairment (3 papers, 2021 to 2022). "CYP27A1 (FC = −1.33, p = 0.03) encodes a cholesterol metabolizing enzyme in the brain, which when reduced leads to increased levels of 27-hydroxycholesterol, a feature of AD disease progression and learning and memory impairment." (PMID 33964983, 2021). "Along with memory impairment, CYP27A1 tg mice have an upregulated brain renin-angiotensin system and reduction in dendritic arborization, spine density of the hippocampus, and levels of long-term memory-related protein Arc (activity-regulated cytoskeleton-associated protein)." (PMID 33676572, 2021). "Notably, CYP27A1-overexpressing mice that produce increased levels of 27-OH develop memory impairment due to, e.g., reduction in neuronal glucose uptake, impaired neuronal branching and reduced synaptic density, inflammation and impairment of the brain renin-angiotensinogen system." (PMID 33676572, 2021).
Stroke (3 papers, 2017 to 2025). Sudden impairment of blood flow to a part of the brain due to occlusion or rupture of an artery to the brain. "Among the non-DKD group, the CYP27A1 rs17470271 genotype showed weak, statistically significant inverse correlations with marital status (ρ = − 0.19, p = 0.03) and stroke (ρ = − 0.16, p = 0.048)." (PMID 40708646, 2025).
Cirrhosis (2 papers, 2006 to 2016). A chronic disorder of the liver in which liver tissue becomes scarred and is partially replaced by regenerative nodules and fibrotic tissue resulting in loss of liver function. "This might be explained by failure of production of CYP27A1 due to mitochondrial damage in the scenario of cirrhosis." (PMID 27399065, 2016). "CYP27A1, an oxidizer of cholesterol, and CYP2E1, a key enzyme in the microsomal ethanol oxidation system, were both up-regulated in most early (CTP class A) cirrhosis samples but significantly down-regulated by more severe, end-stage cirrhosis." (PMID 17121680, 2006).
colitis (2 papers, 2021 to 2022). Inflammation of the colon. "However, it was reported that the expression of Cyp27a1 was not increased in several colitis models when Ch25h was deleted." (PMID 36389671, 2022).
gallstones (2 papers, 2019 to 2020). Solid crystalline precipitates in the biliary tract, usually formed in the gallbladder, resulting in the condition of cholelithiasis. "To date, it has been discovered that the CYP27A1, LXR, PPAR-α, ABCG8 and ABCB11 genes involved in lipid metabolism predispose an individual to gallstone formation." (PMID 32615989, 2020). "Thus, increasing the expression levels of ABCG8, ABCB11, CYP7A1 and CYP27A1 or decreasing the levels of LXR and PPAR-α can stimulate bile acid secretion and efficiently facilitate gallstone dissolution to reverse damage to the hepatocytes." (PMID 32615989, 2020).
hereditary spastic paraplegia (2 papers, 2022 to 2025). Hereditary spastic paraplegias (HSP) comprise a genetically and clinically heterogeneous group of neurodegenerative disorders characterized by progressive spasticity and hyperreflexia of the lower limbs. "We present a patient with a 25‐year history of spastic paraparesis, initially suggestive of hereditary spastic paraplegia (HSP), ultimately diagnosed with CTX associated with a novel CYP27A1 variant of uncertain significance (VUS)." (PMID 39760285, 2025).
hypertriglyceridemia (2 papers, 2018 to 2023). A laboratory test result indicating elevated triglyceride concentration in the blood. "Such an interpretation is consistent with CYP27A1-knockout mice and patients with CYP27A1 loss of function mutations, having hypertriglyceridemia in the brain characterized by behavior and motor dysfunction." (PMID 37107179, 2023). "For example, Cyp27a1 controls the generation of the cholesterol derivative 27-hydroxycholesterol, and knockout of the gene is associated with hypertriglyceridemia." (PMID 29351395, 2018).
hypomyelinating leukodystrophy (2 papers, 2023).
intervertebral disc degeneration (2 papers, 2023 to 2025). "PLCG2 affects neutrophil chemotaxis and inflammation in arthritis, CYP27A1 may serve as a biomarker for intervertebral disc degeneration, and HLA-DQA1 influences neutrophil-mediated immune processes." (PMID 40096134, 2025). "CYP27A1 was identified as a core LRGs in intervertebral disc degeneration." (PMID 37817081, 2023).
liver disease (2 papers, 2015 to 2023). "Increased Cyp27a1 and Cyp7b1 mRNA levels are indicative of a functional upregulation of the alternative pathway to reduce hepatotoxicity and the progression of liver disease to NASH37." (PMID 26619823, 2015).
myocardial infarction (2 papers, 2017 to 2023). Gross necrosis of the myocardium, as a result of interruption of the blood supply to the area, as in coronary thrombosis. "A risk nomogram was established by ACSL1, ALDH2, CYP27A1 and PPARA, demonstrating a good ability for DCM and myocardial infarction prediction." (PMID 37056578, 2023).
periodontitis (2 papers, 2012 to 2025). An acute or chronic inflammatory process that affects the tissues that surround and support the teeth. "It should be considered, however, that although stimuli with periodontal characteristics were used to simulate a periodontitis-like condition, this does not properly model the chronic disease situation in vivo, and can only help to investigate the regulation of CYP27A1 in hGF and hPDLC." (PMID 23251684, 2012).
psoriasis (2 papers, 2022 to 2024). An autoimmune condition characterized by red, well-delineated plaques with silvery scales that are usually on the extensor surfaces and scalp. "Correlation analysis between APOE, CYP27A1, SOAT1, and immune cells revealed positive associations between the expression levels of APOE and CYP27A1 and the abundance of six immune cell types in both psoriasis and leprosy patients." (PMID 38273053, 2024). "Four hub genes APOE, CYP27A1, FADS1 and SOAT1 were downregulated in psoriasis, while were upregulated in leprosy." (PMID 38273053, 2024). "The abundance of 6 immune cell types in psoriasis and leprosy positively correlated with the expression levels of APOE and CYP27A1." (PMID 38273053, 2024). "The ROC curves showed that APOE, CYP27A1, and SOAT1 had high AUC percentages in the GSE74481 dataset (reaching 99.2%, 91.5%, and 85.1%, respectively) and low AUC percentages in the psoriasis integrated dataset (reaching 15.0%, 15.0%, and 29.2%, respectively)." (PMID 38273053, 2024). "Among DEGs, APOE, CYP27A1, and SOAT1 confirmed as critical mutually exclusive genes, exhibiting opposite expression patterns in psoriasis and leprosy." (PMID 38273053, 2024). "In GSE66511 dataset, APOE, CYP27A1, FADS1, and SOAT1 were also significantly downregulated in psoriasis." (PMID 38273053, 2024). "In the GSE54456 dataset, APOE, CYP27A1, FADS1, and SOAT1 showed lower expression levels in psoriasis compared to the control group." (PMID 38273053, 2024). "Box plots showed APOE, CYP27A1, and SOAT1 was upregulated in leprosy tissues, whereas their expression was downregulated in psoriasis tissues." (PMID 38273053, 2024).
Sepsis (2 papers, 2019 to 2025). Sepsis is defined as life-threatening organ dysfunction caused by a dysregulated host response to infection. "Studies have shown that CYP27A1 down regulation in sepsis reduce the amount of circulating bile acid, which may be beneficial for sepsis patients." (PMID 31475010, 2019).
thyroid cancer (2 papers, 2022 to 2023). "CYP27A1 was found to be expressed in both thyroid cancer cells and normal thyrocytes." (PMID 36362448, 2022).
adenomyosis (1 paper, 2025). The growth of endometrial tissue inside the muscular wall of the uterine corpus. "In line with this, a recent study involving a total of 336 women suggested the association between low vitamin D levels and the onset of adenomyosis, supporting the involvement of CYP27A1 in this complex condition." (PMID 41374450, 2025).
amyotrophic lateral sclerosis (1 paper, 2020). Amyotrophic lateral sclerosis (ALS) is a neurodegenerative disease characterized by progressive muscular paralysis reflecting degeneration of motor neurons in the primary motor cortex, corticospinal tracts, brainstem and spinal cord. "CYP27A1 was also identified as a possible candidate gene for amyotrophic lateral sclerosis." (PMID 32714376, 2020).
bile acid synthesis disorder (1 paper, 2025). "Bile acid metabolism assessment in urine showed an elevation of polyhydroxylated bile alcohol glucuronides, suggesting sterol 27-hydroxylase (CYP27A1) deficiency, a bile acid synthesis disorder." (PMID 39897470, 2025).
cervical cancer (1 paper, 2025). A primary or metastatic malignant neoplasm involving the cervix. "This is also in agreement with the effect on cervical cancer cells SiHa and HeLa wherein enhanced VDR expression and activity were observed along with the CYP27A1 and CYP27B1 gene upregulation up on treatment with calcitriol." (PMID 40920750, 2025).